OR5B17 (olfactory receptor family 5 subfamily B member 17)
Description:
Odorant receptor.
Synonyms: OR5B20P; OR11-237
Tractability: Antibody: UniProt places it where antibodies can reach, with medium confidence; UniProt predicts a signal peptide or a membrane-spanning region; its Gene Ontology location is reachable by antibodies, with medium confidence.
Gene: Protein-coding gene on chromosome 11 (58,358,124 to 58,359,069, reverse strand). Ensembl gene ENSG00000197786.
Subcellular location: Cell membrane
Pathways (Reactome):
Sensory Perception: Expression and translocation of olfactory receptors
Gene Ontology:
Molecular function: olfactory receptor activity; G protein-coupled receptor activity
Biological process: G protein-coupled receptor signaling pathway; sensory perception of smell; detection of chemical stimulus involved in sensory perception of smell
Cellular component: plasma membrane; membrane
Genetic constraint (gnomAD): Missense variants: 430 observed, 383.61 expected, observed/expected ratio (o/e) 1.12, 90% interval 1.03 to 1.21. Synonymous variants: 142 observed, 137.24 expected, observed/expected ratio (o/e) 1.03, 90% interval 0.9 to 1.19.
Homologues: Orthologues: chimpanzee OR5B17 (97% identical), dog OR5B17 (76% identical), rat Or5b17 (66% identical). Paralogues in human: OR5B3 (71% identical), OR5B2 (70% identical), OR5B12 (67% identical), OR5B21 (62% identical), OR5AP2 (49% identical), OR5L1 (49% identical), OR8H2 (49% identical), OR9G4 (48% identical), OR5AR1 (48% identical), OR5F1 (48% identical), OR8U1 (48% identical), OR5A1 (48% identical), and 84 more.